GPALPP1 (GPALPP motifs containing 1)
Synonyms: KIAA1704; LSR7; AD029; bA245H20.2
Tractability: PROTAC: UniProt records ubiquitination sites on it; its protein half-life has been measured.
Gene: Protein-coding gene on chromosome 13 (44,989,529 to 45,037,669, forward strand). Ensembl gene ENSG00000133114.
Subcellular location (Human Protein Atlas): Nucleoli rim; Nucleoplasm
Genetic constraint (gnomAD): Loss-of-function variants: 2 observed, 2.13 expected, observed/expected ratio (o/e) 0.94, 90% interval 0.35 to 1.86. That is too few expected variants to judge how well the gene tolerates losing a copy. Missense variants: 46 observed, 45.8 expected, observed/expected ratio (o/e) 1, 90% interval 0.79 to 1.28. Synonymous variants: 13 observed, 19.74 expected, observed/expected ratio (o/e) 0.66, 90% interval 0.43 to 1.05.
Homologues: Orthologues: chimpanzee GPALPP1 (99% identical), macaque GPALPP1 (99% identical), zebrafish gpalpp1 (51% identical), Drosophila melanogaster CG33332 (27% identical).
Diseases named in the same sentence as GPALPP1 in open-access papers:
GPALPP1 is named in the same sentence as 1 disease in open-access papers, as found by Europe PMC text mining. Sharing a sentence is not in itself a finding about the gene and the disease. The quoted sentences say what the papers report.
lymphoma (1 paper, 2021). A malignant (clonal) proliferation of B- lymphocytes or T- lymphocytes which involves the lymph nodes, bone marrow and/or extranodal sites. "Of the 579 overrepresented proteins, six proteins were found in at least 20-fold higher abundance in lymphoma patients (NUCKS1, SLC14A1, GPALPP1, ADPRH, CD72, PRDM15)." (PMID 33562532, 2021).